LEP (leptin)
Diseases named in the same sentence as LEP in open-access papers (continued):
Sharing a sentence is not in itself a finding about the gene and the disease.
breast cancer (continued). "Next, we examined the effect of leptin (200 ng/mL) on metastatic potential in MCF-7 and SK-BR-3 breast cancer cells using a transwell assay." (PMID 32836215, 2020). "Breast cancer has the seventh strongest correlation (Rho = 0.177) between average FGFR1 mRNA and average leptin mRNA among all primary cancers that showed the highest significance between FGFR1 mRNA and leptin mRNA (p = 3.17 × 10−9)." (PMID 33019728, 2020). "Together, these data suggest that miR-34a repression was crucial for leptin/OBR induced PAI-1 expression in the interaction between adipocytes and breast cancer cells." (PMID 33371368, 2020). "Leptin-induced IL-8 activation via intracellular signaling molecules, such as STAT3, Akt, and ERK 1/2, facilitates EMT of breast cancer cells." (PMID 33123472, 2020). "Recently, leptin was observed to stimulate SREBP-1 expression to induce metabolic reprogramming of cancer cells, which is crucial for the growth of breast cancer cells." (PMID 33371368, 2020). "Therefore, increased leptin sensitivity may likely support AIR in breast cancer cells." (PMID 32260113, 2020). "LEP and CLDN1 had been both shown to induce cellular migration and epithelial to mesenchymal transition (EMT) in breast cancer cells, further suggesting a FAM83H-AS1 role in the early steps of migration." (PMID 32839509, 2020). "We used immunohistochemistry (IHC) to assess LEP, LEPR, ADIPOQ, ADIPOR1, and ADIPOR2 expression in breast tumor tissue microarrays among a sample of 720 women recently diagnosed with breast cancer (540 of whom self-identified as Black)." (PMID 32046756, 2020). "Mechanistically, we elucidated that leptin/OBR further activated STAT3 to promote PAI-1 expression via miR-34a–dependent and miR-34a–independent mechanisms in breast cancer cells." (PMID 33371368, 2020). "With the present study, we investigated the expression and the intracellular distribution of KHDRBS1, leptin, and LEPR in bone metastasis from breast carcinoma and looked for eventual correlations between them." (PMID 33213024, 2020). "Here, we considered bone metastasis derived from breast carcinoma to investigate the expression in bone metastasis of biomarkers KHDRBS1, leptin, LEPR, and adiponectin." (PMID 33213024, 2020). "In this study, we evaluated the role of leptin in the activation of FAK and Src kinases, and their roles in cell migration, metalloproteases secretion, and invasion in a cultured cell model of breast cancer." (PMID 31671408, 2019). "We utilized the breast cancer cell lines MCF7 and MDA-MB-231 and found that leptin activates FAK and Src." (PMID 31671408, 2019). "In this report, we described, for the first time, a novel mechanism by which the adipokine leptin increases exosome generation from both estrogen receptor-positive MCF-7 and triple-negative MDA-MB-231 breast cancer cells." (PMID 31336913, 2019). "Leptin activates estrogen receptor (ER) signaling, as well as the JAK/STAT3 and PI3K/AKT signaling pathways, promoting the proliferation of breast cancer cells." (PMID 31500658, 2019). "It has been reported that estradiol administration increases leptin and ObR expression in ER-positive MCF-7 breast cancer cell lines." (PMID 30634494, 2019). "In a randomised controlled trial examining the effects of exercise in overweight or obese breast cancer survivors, circulating biomarkers (insulin, IGF‐1, adiponectin and leptin) were significantly improved post‐intervention, compared to usual care." (PMID 31016867, 2019). "Regarding angiogenesis regulation by leptin in breast cancer, some studies have shown that the activation of HIF-1α and NF-κB by leptin are essential in the regulation of VEGF, which promotes angiogenesis." (PMID 31380268, 2019). "Leptin also interfered with the estrogen antagonist ICI 182,780 action by reducing its effects in MCF-7 breast cancer cells." (PMID 30634494, 2019).
breast cancer (continued). "In this study, we utilized the breast cancer cell lines MCF7 and MDA-MB-231 to determine the effect of leptin on FAK and Src kinases activation, cell migration, metalloprotease secretion, and invasion." (PMID 31671408, 2019). "It has been reported that leptin can upregulate the expression of STAT3-CPT1B and plays an important role in maintaining the stem and drug resistance of breast cancer cells." (PMID 31440472, 2019). "Over-expression of both LEP and LEPR in CRC, along with similar findings in our previous studies with breast carcinoma and related works of other authors suggest strong association of LEP/LEPR system with carcinogenesis." (PMID 31592340, 2019). "In this review, we focus on the molecular role of leptin as an inducer of EMT and its implications in breast cancer." (PMID 30404206, 2018). "Together, our results suggest that pharmacological inhibition of IL-6 and leptin as well as the downstream JAK/STAT3 and PI3K/AKT signaling pathways can decrease PLOD2 expression and suppress breast cancer metastasis." (PMID 30563531, 2018). "Leptin addition attended to block ICI 182,780-mediated therapeutic effects on breast cancer MCF-7 cell proliferation, suggesting the involvement of estrogen signaling axis in drug resistance." (PMID 29682217, 2018). "The secretion of IL-6 and leptin was increased in the supernatant of adipocytes cocultured with MDA-MB-231 and MDA-MB-468 breast cancer cells compared with 3 T3-L1 preadipocytes and adipocytes." (PMID 30563531, 2018). "a qRT-PCR analysis of the relative expression levels of IGF-BP1, PAI-1, IL-6, MIF, TIMP-1, TIMP-2 and leptin in adipocytes and adipocytes cocultured with MDA-MB-468 (MB-468) breast cancer cells." (PMID 30563531, 2018). "b Dot hybridization analysis of IL-6 and leptin secretion in 3 T3-L1 preadipocytes, adipocytes and adipocytes cocultured with MDA-MB-468 (MB-468) breast cancer cells." (PMID 30563531, 2018). "Further investigation revealed that adipocyte-derived IL-6 and leptin promote PLOD2 expression, thus facilitating breast cancer metastasis." (PMID 30563531, 2018). "To confirm the effects of adipocyte-derived IL-6 and leptin on the regulation of distal organ seeding and growth of metastatic tumor cells, we conducted tail vein metastasis assays using the MDA-MB-231 human breast cancer cell line." (PMID 30563531, 2018). "Leptin increases Notch and increased proliferation and upregulation of VEGF in breast cancer cells depends on intact Notch signaling." (PMID 29587359, 2018). "In conclusion, leptin promotes the progression of breast cancer through the induction of the EMT program, promoting a more aggressive phenotype in breast cancer cells." (PMID 30404206, 2018). "A 3-day exposure to leptin significantly increased PLOD2 expression and activated phosphorylation of STAT3 and AKT in MDA-MB-231 and MDA-MB-468 breast cancer cells." (PMID 30563531, 2018). "Our study reveals that adipocyte-derived IL-6 and leptin promote PLOD2 expression by activating the JAK/STAT3 and PI3K/AKT signaling pathways, thus promoting breast cancer metastasis." (PMID 30563531, 2018). "Leptin treated MCF7 and MCF10AT1 breast cancer cells formed significantly more mammospheres than control cells." (PMID 28542577, 2017). "We propose that this occurs in an autocrine manner, where leptin induces TGFB1 expression and secretion, which then acts on TGFBRI and TGFBRII receptors of breast cancer cells." (PMID 28542577, 2017). "To characterize apoptotic roles and pathways of Leptin and SAHA in breast cancer cells, we used a proteome profiler antibody array to measure the changes in apoptosis-related protein expression in MCF-7 and MDA-MB-231 cells with Leptin and SAHA treatment." (PMID 27926517, 2017). "There are reports of the inhibitory action of Aca-1 and Allo-aca on leptin-stimulated proliferation of MCF-7 and MDA-MB231 breast cancer cells, and D-Ser and DDD on the proliferation of MCF-7 cells." (PMID 28861689, 2017).
breast cancer (continued). "It is known that ADIPO and LEP activate AMPK and Akt signaling pathways, respectively, and these pathways antagonize each other in breast cancer cells." (PMID 28873415, 2017). "The effect of leptin over cell growth has been determined in MCF-7, MDA-MB231, SK-BR-3, T47D, and ZR-75-1 breast cancer cell lines, mediated by diverse signaling pathways when a single stimulus of the protein is applied and is incubated between 24 and 96 h." (PMID 29311755, 2017). "This study strengthens the potential significance of leptin in breast cancer progression and identifies the TGFB1 receptor as a functionally important and novel route mediating the actions of leptin in promoting metastasis." (PMID 28542577, 2017). "Combining with real-time monitor data for Leptin and SAHA, we treated MCF-7 cells or MDA-MB-231 cells for 32 hours with 0.625 nM Leptin or 5 μM SAHA and measured viability and apoptosis for the breast cancer cells." (PMID 27926517, 2017). "Additional studies suggest that tumors in obese breast cancer patients, particularly ER/PR-negative tumors, are dependent of growth factors such as insulin, insulin growth factor 1 (IGF1), and leptin." (PMID 28607775, 2017). "In order to further clarify the impacts of Leptin and SAHA on breast cancer cell proliferation, we used cell cycle real-time PCR array to target mRNA changes of associated factors that can either positively or negatively control the transition of cell cycle." (PMID 27926517, 2017). "We have also identified binding of TGFB1 to its receptor as a new pathway contributing to the leptin-induced EMT and CSC effects on breast cancer cells." (PMID 28542577, 2017). "Inhibitors of TGFB1 are in currently in phase III clinical trials in other malignancies, thus identifying the connection between leptin and TGFB1 will open new therapeutic opportunities for improving outcomes for obese breast cancer patients." (PMID 28542577, 2017). "For this, we first assessed the effects of leptin on AMPK phosphorylation in MCF-7 and MDA-MB-231 breast cancer cells." (PMID 29312618, 2017). "High levels of pro-angiogenic factors, leptin, IL-1, Notch and VEGF (ligands and receptors), are found in breast cancer and commonly correlated with metastasis." (PMID 27472371, 2016). "In human breast cancer MCF-7 and MDA-MB-231 cells, leptin treatment promoted VEGF secretion and increased cell proliferation and migration compared to controls, whereas treatment with adiponectin exerted the opposite effect." (PMID 27983683, 2016). "Our previous study showed that leptin and interleukin 8(IL-8) induced EMT in breast cancer cells via the PI3K/AKT signal pathway, and this signal pathway was a significant canonical signaling pathway in leptin-induced signals." (PMID 27769315, 2016). "Co-culture of adipocytes and breast cancer cells per se increased the secretion of VEGF and leptin and enhanced the effects of estradiol compared to culture of either cell type alone." (PMID 27059487, 2016). "Of note, in breast cancer, Wnt-1-MTA1-β-catenin pathway is activated by Leptin, and is considered a critical therapeutic target." (PMID 27657035, 2016). "Co-culture of adipocytes and ER+ breast cancer cells induced alterations per se with increased extracellular levels of VEGF and leptin, and enhanced the effects of estradiol compared with either cell type cultured alone." (PMID 27059487, 2016). "Leptin up-regulates Notch1-4/JAG1/Dll-4, while Notch targets genes, Hey2 and Survivin, together with IL-1 and VEGF/VEGFR-2 in breast cancer cells." (PMID 27472371, 2016). "Recent studies from our lab and others have revealed myriad oncogenic effects of leptin including induction of growth, epithelial-mesenchymal-transition (EMT), invasion and migration potential of breast cancer." (PMID 26036628, 2015).
breast cancer (continued). "Striving to develop effective, clinically viable leptin-antagonists using bioactive compounds, we recently discovered that HNK is capable of inhibiting breast cancer growth in hyperleptinemic state." (PMID 26359358, 2015). "These discoveries sparked our interest in investigating the efficacy of HNK as a novel inhibitor of leptin-induced EMT and stemness in breast cancer." (PMID 26359358, 2015). "Given their putative relevance to mammary tumour growth, serum VEGF, leptin and PGE metabolites were also quantified by separate ELISA experiments in both untreated strains and those treated with DMBA alone or DMBA + ROSI." (PMID 25889730, 2015). "Leptin produced by MSCs enhanced expression of EMT and metastasis genes (SERPINE1, MMP-2, and IL-6) in breast cancer cells." (PMID 26694366, 2015). "have demonstrated the existence of a bidirectional crosstalk between leptin and insulin-like growth factor I (IGF-I) signalling, mediated by synergistic transactivation of EGFR, which influences breast cancer cell invasion and migration." (PMID 25721149, 2015). "Consequently, reductions in circulating leptin, with or without maintained weight loss, could elicit considerable breast cancer preventive effects." (PMID 24790820, 2014). "In parallel, it has been shown that leptin and its receptor initiate EMT via PI3K/Akt signaling pathway and β-catenin stabilization and nuclear translocation in breast cancer cells." (PMID 25505738, 2014). "Additional studies have provided evidence to support a role for an inverse association between the A/L ratio and breast cancer risk and prognosis, suggesting the balance of adiponectin and leptin, rather than either biomarker alone, may also be clinically significant." (PMID 24790820, 2014). "In particular, IFNγ, leptin, TGFβ1, TIMP1, TIMP2, thrombopoietin and VEGF levels were significantly inhibited by anandamide in the conditioned medium of MDA-MB-231 breast cancer cells." (PMID 25147760, 2014). "Leptin, OB-R, Notch4, JAG1 and, IL-1R tI were detected in more than 60% of breast cancer (ER+, ER- and, TNBC)." (PMID 24716804, 2014). "Analysis of data published on expression of Notch, leptin, OB-R, IL-1R tI, and VEGF/VEGFR2 in breast cancer showed several correlations with tumor progression/angiogenesis." (PMID 24716804, 2014). "Immunohistochemical studies have shown that leptin, adiponectin and their receptors (Ob-R, AdipoR1 and AdipoR2) are detected in the cytoplasm of MCF-7 breast cancer cells." (PMID 23750285, 2013). "Therefore, it appears that leptin might influence the development of breast cancer." (PMID 23826274, 2013). "Furthermore, the positive effects of estrogen on leptin expression in ASCs suggest a potential mechanism by which these ASCs are elicited to influence breast cancer cell proliferation and suggest a new avenue to be explored for breast cancer treatment in obese patients." (PMID 24176089, 2013). "It has proposed an autocrine signaling function as breast cancer are able to produce and secrete IGF-1 and leptin and express cell surface receptors for both ligands." (PMID 24340245, 2013). "A complex crosstalk between leptin, Notch and IL-1 (NILCO) that induces VEGF/VEGFR2 is found in breast cancer." (PMID 24202338, 2013). "In breast cancer cells, HIF/p300 complex bound the upstream leptin regulatory sequences of the proximal leptin gene promoter." (PMID 24202338, 2013). "The human ER positive MCF-7 breast cancer cell line has been used extensively as a model to investigate mitogenic adipokine signaling in human breast cancer cells and MCF-7 cells, express leptin, collagen VI, and IGF receptors." (PMID 24171117, 2013). "Here, we showed that leptin was able to increase VEGF secretion by MCF7 and MDA-MB-231 breast cancer cell lines." (PMID 23554900, 2013).
breast cancer (continued). "This study demonstrates that EE housing influenced normal mammary gland development and inhibited mammary tumor growth resulting in a marked decrease in intratumoral COX-2 activity and an increase in the plasma ratio of adiponectin/leptin levels." (PMID 23272114, 2012). "The study further reported that using the EGFR inhibitors, lapatinib and erlotinib, in an in vitro model system for metastasis after application of leptin and IGF-I reduced invasion and migration of breast cancer cells." (PMID 22295251, 2012). "We have found that EE housing influenced normal mammary gland development and inhibited mammary tumor growth resulting in a marked decrease in intratumoral COX-2 activity and an increase in the plasma ratio of adiponectin/leptin levels." (PMID 23272114, 2012). "Leptin and interleukin-1 (IL-1) upregulate vascular endothelial growth factor (VEGF), promote angiogenesis and are related to worse prognosis of breast cancer." (PMID 21139583, 2011). "Leptin induction of proliferation/migration and upregulation of VEGF/VEGFR-2 in breast cancer cells were related to an intact Notch signaling axis." (PMID 21731759, 2011). "Therefore, leptin and IL-1 may have synergistic functions in breast cancer progression." (PMID 21139583, 2011). "High levels of pro-angiogenic factors, leptin, IL-1, Notch and VEGF (ligands and receptors), are found in breast cancer, which is commonly correlated with metastasis and lower survival of patients." (PMID 21731759, 2011). "Several genetic and pharmacologic approaches were used to determine how leptin regulates Notch (ligands/receptors/targets) and the impact of Notch signaling on leptin-induced VEGF/VEGFR-2 expression in breast cancer cells." (PMID 21731759, 2011). "Leptin uses several signaling pathways, including the activation of HIF-1α and NF-κB, for the upregulation of VEGF in breast cancer cells under normoxic conditions." (PMID 21731759, 2011). "Intratumoral hypoxia in breast cancer is marked by coordinated expression of such markers as HIF-1α, Glut-1, leptin and ObR." (PMID 20569445, 2010). "A bidirectional crosstalk between leptin and insulin-like growth factor-I (IGF-I) signaling was also shown to stimulate invasion and migration of breast cancer cells." (PMID 20030801, 2009). "We analyzed the expression of leptin and ObR by IHC in HER2-positive and HER2-negative breast cancers characterized in Table." (PMID 18945363, 2008). "In the present study, we analysed LEP (-2548) G/A and LEPR Q223R genotypes in a series of breast cancer cases and normal controls." (PMID 16504019, 2006). "Some authors have demonstrated that leptin increase cell proliferation which is an essential element for tumor metastasis, through cell progression in MCF-7 human breast cancer cells with up-regulation of PKC-α, PPARγ and PPARα." (PMID 16504019, 2006). "The LEP (-2548) G/A and LEPR Q223R Genotype distributions in Control Subjects and in Patients with Breast Carcinoma." (PMID 16504019, 2006). "We used the polymerase chain reaction and restriction enzyme digestion to characterize the variation of the LEP and LEPR genes in 308 unrelated Tunisian patients with breast carcinoma and 222 healthy control subjects." (PMID 16504019, 2006). "However, recent results from epidemiological studies do not support the hypothesis that plasma leptin is a risk factor for breast cancer." (PMID 16168107, 2005). "In conclusion, leptin was found to upregulate MTA1 expression via the Ob-R/STAT3 signaling pathway, which in turn promotes VM by regulating the expression of VM-related proteins in breast cancer cells." (PMID 40565190, 2025). "The Western blot results showed that leptin-induced MTA1 upregulation was suppressed by all these inhibitors, confirming that leptin regulates MTA1 expression via the Ob-R/STAT3 signaling pathway in breast cancer cells." (PMID 40565190, 2025).